LAMP2 (lysosome associated membrane protein 2)
Diseases named in the same sentence as LAMP2 in open-access papers (continued):
Sharing a sentence is not in itself a finding about the gene and the disease.
Danon disease (continued). "Only one patient harbored a heterozygous frameshift variant in LAMP2, a secondary CMP gene associated with Danon disease." (PMID 35288587, 2022). "Several large deletions that alter the LAMP2 exon copy number have been described in male patients with Danon disease and involve repetitive sequence motifs, such as Alu-mediated or TA-rich repeat elements." (PMID 36009380, 2022). "In summary, the current work establishes LAMP2 KO iPSC-CMs for the modeling and study of the pathologic mechanism of Danon disease." (PMID 36671453, 2022). "As the disease is due to phenotypic demonstration of the diseased allele, activating the previously silenced normal X-chromosome with the wildtype LAMP2 gene will rescue the diseased phenotype in the heterozygous female Danon disease patient." (PMID 34360897, 2021). "LAMP2 expression analysis was performed in different tissue samples from females related to boys with Danon disease." (PMID 33925963, 2021). "Lamp2 is also known to promote autophagic flux and samples from patients of Danon disease present accumulated LC3 positive autophagosomes and undigested lipofuscin, indicating defective autophagic flux." (PMID 32117965, 2020). "Humans with Danon disease and Lamp2-knockout mice both show hypertrophic cardiomyopathy characterized by accumulated autophagic vacuoles filled with polymorphic contents, which are mainly the result of disrupted macroautophagy." (PMID 32117965, 2020). "As mentioned, Pompe disease, Danon disease, Fabry disease, and MPS type I are caused by mutations in the GAA, LAMP-2, α-galactosidase A (a-Gal A), and the α-L-iduronidase (IDUA) genes, respectively." (PMID 32012649, 2020). "Pre-excitation and conduction disease put the focus on LAMP2 (Danon disease), PRKAG2, TTR (amyloidosis) or GLA (Fabry disease)." (PMID 30393635, 2018). "The metabolic genes tested were Anderson-Fabry disease (GLA), Danon disease (LAMP-2), and familial Wolff-Parkinson-White syndrome (PRKAG2)." (PMID 29637036, 2018). "Consequently, it may help to understand the mechanisms involved with other diseases, related not only to LAMP-2 deficiency, such as Danon disease, but also with some lysosomal storage maladies or any genetic disorder in which impairment in plasma-membrane repair is observed." (PMID 28586379, 2017). "Reduced fusion has been shown in cells depleted of LAMP2 as demonstrated in LAMP2 knockout mice which showed accumulation of autophagic vacuoles in several tissues and in patients with Danon disease." (PMID 27627761, 2016). "Our data contribute to the understanding of intellectual dysfunction observed in Danon disease patients and highlight the role of LAMP-2 within the central nervous system, particularly the hippocampus." (PMID 25637286, 2015). "In conclusion, our data suggest a novel role of LAMP-2 for lysosomal and autophagic clearance within hippocampal neurons and contribute to the understanding of neuropathology in Danon disease." (PMID 25637286, 2015). "Danon Disease is an X-linked dominant lysosomal storage disorder caused by pathogenic variants in the LAMP2 gene, which encodes the lysosome-associated membrane protein-2 (LAMP-2)." (PMID 41614773, 2025). "Additionally, eight were syndromic patients: four with Noonan syndrome (PTPN11 and biallelic LZTR1), two with Danon disease (LAMP2), two with Carvajal syndrome (DSP), and one with atypical glycogen storage disease (PRKAG2)." (PMID 40642871, 2025). "Further support for a loss-of-function mechanism involving LAMP2B was demonstrated by phenotypic improvement of Lamp2 knockout mice, which lack all three isoforms and have key clinicopathological features of Danon disease, following gene-transfer treatment with AAV9-LAMP2B." (PMID 39501809, 2024). "However, LAMP2 deficiencies are also reported to cause retinopathies and RPE degeneration independently or in association with Danon disease." (PMID 37359372, 2023).
Danon disease (continued). "In addition, a tandem and likely Alu-mediated duplication of exons 4–5 in the LAMP2 gene has been identified in two brothers with typical Danon disease phenotype and was mosaically distributed in the somatic tissues of their clinically asymptomatic mother." (PMID 36009380, 2022). "A 17-year-old female patient with hypertrophic cardiomyopathy and pre-excitation in ECG (after two-fold RF ablation—radiofrequency catheter ablation), treated with Sotalol, in whom genetic testing revealed heterozygous deletion in the LAMP2 region typical for Danon disease." (PMID 36141934, 2022). "In both studies, reduced LAMP2 expression in heterozygous female patients with Danon disease might result from random XCI; however, the patterns of XCI were not determined." (PMID 33925963, 2021). "While dysregulated LAMP1 expression does not cause apparent lysosomal defects, LAMP2 deficiency impairs lysosomal degradation and autophagy and is implicated in Danon disease." (PMID 34445748, 2021). "Data from Danon disease samples obtained with Raman, AFM, transcriptome, and metabolome analyses suggest that LAMP-2 deficiency triggers a profound metabolic switch, possibly associated with rerouting of metabolism toward alternative strategies to maintain NAD+/ NADH ratio." (PMID 32751926, 2020). "However, studies in which the Lamp2 gene is deleted in mice result in a Danon’s disease-like phenotype and accumulation of autophagosomes." (PMID 32998777, 2020). "The deficiency of lysosomal-associated membrane protein-2 (LAMP-2), which causes a disruption in the autophagosome–lysosome machinery, also leads to vacuolar myopathy, cardiac hypertrophy and severe cardiac dysfunction, which is known as Danon's disease." (PMID 27512143, 2016). "Furthermore, the phenotype of Vps15 muscle KO mice was highly reminiscent of the phenotype observed in muscles of Lamp2 knockout mice (model of Danon disease) which presented a similar accumulation of glycogen and p62, as well as sarcolemmal features." (PMID 23630012, 2013). "Danon disease (GSD IIb, OMIM #300257) is an X-linked disease caused by mutations in LAMP2 and has overlapping symptoms with Pompe disease, including diffuse hypotonia and hypertrophic cardiomyopathy." (PMID 32351971, 2020). "The lack of LAMP2 may cause Danon disease in patients, showing various types of cytoplasmic vacuole accumulation,including the accumulation of pancreatic acinar cells." (PMID 29541382, 2018). "Danon disease is caused by loss of LAMP2 itself, rather than a glycosylation defect, but the observed LAMP2 underglycosylation in TMEM165-depleted cells suggests an avenue by which TMEM165 dysfunction might indirectly affect lysosomal proteins relevant to cardiac pathology." (PMID 41583011, 2025). "Glycogen storage cardiomyopathy usually contains Pompe disease (PD), PRKAG2 syndrome, and LAMP2 syndrome." (PMID 39465141, 2024). "All-encompassing LAMP2 deficiency (leading to lack of all splicing variants, LAMP-2A/B/C) had previously been studied in the context of Danon disease, a complex dominant genetic disorder caused by LAMP2 mutations and characterized by severe cardiomyopathy." (PMID 41168502, 2025). "In three female patients, genetic testing revealed Danon disease (LAMP2), which had not been clinically suspected prior to testing." (PMID 41440877, 2025). "Tissue staining showing the absence of LAMP-2 protein can confirm the diagnosis, but it is not required in all of the Danon disease cases." (PMID 37686045, 2023). "Of the 17 known GSDs, Pompe disease (GSD II) and Danon disease (also classifiable as an integral membrane protein disorder) are categorized as LSDs given their involvement of the lysosomal acid α-glucosidase (GAA) and LAMP2, respectively." (PMID 32435656, 2020).
Danon disease (continued). "Two diverse populations of hiPSCs can be generated from heterozygous female patients with Danon disease: one with WT LAMP-2 expression and the other with mutant LAMP-2 expression, which is due to the random inactivation of the X chromosome carrying the WT or mutant LAMP2." (PMID 32012649, 2020). "As LAMP-2 was completely absent in muscle from the proband in Family 17, the family was finally given a diagnosis of Danon disease." (PMID 30413001, 2018). "Importantly, variants in classic sarcomeric/contractile genes comprised 42.8%, and genotype-negative patients were virtually absent, while 21.4% of female patients were diagnosed with Danon disease (LAMP2)." (PMID 41440877, 2025). "Moreover, and as exemplified by the severe phenotype observed both in LAMP-2 deficient mice as well as in patients suffering from Danon’s disease associated with a loss of LAMP-2 function, a therapeutic approach modulating LAMP-2 seems not practical." (PMID 36010638, 2022). "While the pathologic mechanisms of Pompe disease are not clear, more is known about Danon disease, an X-linked lysosomal disorder caused by mutations in the LAMP2 gene (lysosome-associated membrane protein 2) and associated with cardiomyopathies, including DCM and HCM." (PMID 31842377, 2019). "Notably, disruption of autophagic pathway are likely to lead to dysfunction of autophagy, for instance suppression of constitutive cardiomyocyte autophagy, or impairment of late stages of autophagy in the absence of LAMP2 in patients with Danon disease." (PMID 27322431, 2016).
cardiomyopathy (45 papers, 2008 to 2026). A disease of the heart muscle or myocardium proper. "Conversely, when a skewed XCI favoring the mutant allele occurs, the majority of cardiomyocytes show LAMP2 deficiency, and the overlap of nuclear domains in skeletal muscle is insufficient, resulting in early onset and severe cardiomyopathy and myopathy." (PMID 37628591, 2023). "Mutations in LAMP2 manifest phenotypically with the characteristic triad of fixed, progressive, proximal myopathy, cardiomyopathy, and intellectual disability with onset in adolescence." (PMID 32316520, 2020). "In the past two decades, however, a preponderance of evidence suggests a large genetic contribution to this condition when observed in the setting of cardiomyopathy, including mutations in the gene of LAMP2 (Liu, Xue, Wu, & Hu, 2016)." (PMID 30929317, 2019). "Female carriers of LAMP2 mutations are also susceptible to arrhythmias, HF and cardiomyopathy." (PMID 41425985, 2025). "In an open‐label Phase 1 clinical trial, a single IV administration of RP‐A501 (AAV9.LAMP2B) was shown to effectively deliver and transduce cardiomyocytes in patients afflicted with DD—an X‐linked monogenic cardiomyopathy attributed to mutations in the LAMP2 gene." (PMID 39465141, 2024). "Cardiomyopathy in LAMP2 carriers may be associated with conduction defects, such as Wolf–Parkinson–White syndrome, which may be complicated by cardiac arrest secondarily leading to ischemic stroke." (PMID 32316520, 2020). "More recently, the irregular distribution of LAMP-2 in cardiac muscle fibers has been raised as a major determinant of the development of cardiomyopathy in females." (PMID 39456205, 2024). "DMD and LAMP2 mutations are very rare causes of DCM; notably, most known DCM-causing mutations affect the sarcomere, causing cardiomyopathy through impaired force generation or reduced contractility in the heart." (PMID 33467574, 2021). "The mean (±SD) number of genes per panel was 33±25, including 8±0.3 sarcomere genes, 4±2 storage cardiomyopathy, and RASopathy genes (LAMP2, PRKAG2, TTR, GLA, PTPN11, RIT1, and RAF1) and 22±23 other genes (range, 0–75)." (PMID 30681346, 2019). "In these mice, the knockout of LAMP-2 leads to cardiomyopathy and an increase in the amount of autophagy/lysosome compartments in many tissues." (PMID 18958159, 2008). "On the other hand, the deletion of LAMP-2 protein was observed in the muscle of a few girls with early onset myopathy and cardiomyopathy, which may reflect an extremely skewed X-chromosome inactivation pattern (XCI) that favors the mutant allele." (PMID 39456205, 2024). "Similarly, LAMP-2-deficient mice displayed increased autophagic vacuole accumulation and could not degrade proteins, thereby promoting cardiomyopathy." (PMID 31277291, 2019). "A detrimental heterogeneous distribution of LAMP2 (rather than an overall protein reduction) is crucial for the development of cardiomyopathy." (PMID 37628591, 2023). "In fact, our findings suggest that a 50% reduction in LAMP-2 may prevent the development of myopathy, but not cardiomyopathy." (PMID 30413001, 2018). "When a random XCI occurs, the overlap of nuclear domains can rescue LAMP2 expression in skeletal muscle fibers but not in cardiomyocytes (which do not regenerate), thus explaining why the majority of female patients developed cardiomyopathy but not skeletal myopathy." (PMID 37628591, 2023).
breast carcinoma (22 papers, 2015 to 2025). "As a demonstration, here, we showed in vivo, in a xenograft model of osteolytic BM from breast carcinoma, that acidifying carcinoma cells expressing LAMP-2 and V-ATPase are closely associated with actively resorbing OC." (PMID 34124067, 2021). "This attempt was made in the light of a recently published study where presumptive low pH zones in breast cancer tissues were identified to be associated with enhanced LAMP2 surface localization in vivo and extracellular acidification was shown to generate the same effect in vitro." (PMID 28299282, 2017). "The mRNA expression of lysosomal-associated membrane protein 2 (LAMP2), the main membrane protein of lysosomes, was significantly suppressed in breast cancer cells after Doxo treatment at both 72 and 96 h." (PMID 37993606, 2023). "Experimental studies have shown that CDKN2A, PSAT1, HMGB1, ELAVL1, and SLC7A11 were up-regulated in TNBC, ASNS and LAMP2 were up-regulated in breast cancer and CAV1 was down-regulated in breast cancer, and HELLS was up-regulated in other tumors." (PMID 36568247, 2022). "For example, the absence of glycolytic metabolism and vascularization produces an acidic microenvironment in the early stages of in situ breast cancer, leading to an increase in LAMP2 on the plasma membrane and tumor progression." (PMID 35530327, 2022). "In breast cancer, high expression of LAMP2 is also detected, and its high expression is significantly associated with tumor progression." (PMID 34124097, 2021). "Localization of LAMP2 to the plasma membrane is recently evidenced to protect breast cancer cells from acidosis and surface hydrolysis." (PMID 28299282, 2017). "They extended their studies to breast cancer patients and showed enhanced levels of LAMP2 in breast cancer tumors as compared to normal tissue." (PMID 27627761, 2016). "To better investigate the biodistribution of LAMP2 protein, we stained whole-mount breast cancer samples from patients of different stages (I–IV)." (PMID 26658462, 2015). "Because mRNA levels are not necessarily related to the protein levels and localization, protein expression of LAMP2 was investigated by IHC of TMAs on patient sample biopsies from different stages of breast cancer." (PMID 26658462, 2015). "In breast cancer patient samples, there is a high correlation of LAMP2 mRNA and protein expression with progression." (PMID 26658462, 2015). "Further, treatment of mice bearing breast cancer xenografts with bicarbonate buffer therapy to raise tumour pH, resulted in lower-LAMP2 expression compared with untreated controls." (PMID 26658462, 2015). "Immunohistochemistry (IHC) of human breast cancer tissue microarrays (TMAs) shows increased expression of LAMP2 with increasing tumour grade." (PMID 26658462, 2015). "A reduction in LAMP-2 expression has been directly linked to low CMA activity as well as increased levels of oxidized proteins in aged livers and breast cancer cells." (PMID 25637286, 2015). "Recently, LAMP2 has been considered a valuable biomarker of tumor acidosis, and its overexpression has been correlated with breast cancer progression to malignant stages, as it allows the adaptation and survival of cancer cells in low-pH tumor microenvironments." (PMID 40551171, 2025). "Similarly, retarded electrophoretic mobility of LAMP2 was observed in AEPKD mouse breast cancer cell line 4T1." (PMID 39743643, 2025). "•LAMP2 from RBCs is a prognostic biomarker in breast cancer patients." (PMID 36519745, 2022). "We then measured the positivity of each core for LAMP2 in different stages of breast cancer." (PMID 26658462, 2015). "The discovery of LAMP2 as a biomarker and further observation of its presence on cell surface of acid-adapted cells has also led us to propose a new adaptation mechanism for chronic acidosis in solid tumours, such as breast cancer." (PMID 26658462, 2015). "We then sought to investigate LAMP2 expression in breast cancer patient tumours." (PMID 26658462, 2015).
breast carcinoma (continued). "Similarly, 500 nM Abe down-regulated LAMP2 expression in breast cancer cells." (PMID 37993606, 2023). "Treatment TNBC and ERBB2+ breast cancer cells with neratinib also reduced the expression of p62 SQMT1, LAMP2, HDAC6, DRP-1, mitochondrial HSP70, HSP70, HSP90 and GRP78." (PMID 29163826, 2017). "Validation studies confirmed LAMP2 expression upregulated by acidosis by reverse transcription–PCR and western blotting in MCF-7 and other breast cancer cell lines." (PMID 26658462, 2015). "In addition, we validated the prognostic value of LAMP2 in a variety of cancers including LUAD, GBMLGG, breast cancer, colorectal cancer, blood cancer (follicular lymphoma), and soft tissue cancer (liposarcoma) using PrognoScan based on the GEO dataset." (PMID 35530327, 2022). "The strongest colocalization observed was a3 with LAMP2, particularly in MB231 and MCF10CA1a cells, suggesting the presence of a significant number of a3-containing V-ATPases in lysosomes of invasive breast cancer cells." (PMID 27323815, 2016). "Breast cancer cells lacking STARD7 also showed elevated levels of LAMP1 or LAMP2, which, together with flow cytometry analyses using Lysotracker, demonstrates that STARD7 deficiency in both MCF7 and MDA‐MB231 but not in T47D cells led to an increased in lysosomal biomass, a hallmark of autophagy." (PMID 40443279, 2025). "Although LeY carried by surface LAMP-1 has been suggested to be involved in cell migration in breast cancer, no studies so far showing the correlation of FUT1-modified LAMP-1 and/or LAMP-2 with lysosomal localization and autophagic process." (PMID 27560716, 2016). "In addition, the possible ferroptosis mechanisms of CDKN2A, PSAT1, SLC7A11, LAMP2, CAV1, and HMGB1 in TNBC and ASNS, ZFP69B, ELAVL1, TF, HELLS, and DPP4 in breast cancer have not been reported." (PMID 36568247, 2022).